C10orf53 (chromosome 10 open reading frame 53)
Synonyms: Em:AC069546.1
Tractability: No criterion of Open Targets' tractability assessment is met for any kind of drug.
Gene: Protein-coding gene on chromosome 10 (49,679,651 to 49,710,261, forward strand). Ensembl gene ENSG00000178645.
Genetic constraint (gnomAD): Loss-of-function variants: 8 observed, 9.03 expected, observed/expected ratio (o/e) 0.89, 90% interval 0.52 to 1.57. That is too few expected variants to judge how well the gene tolerates losing a copy. Missense variants: 117 observed, 111.42 expected, observed/expected ratio (o/e) 1.05, 90% interval 0.9 to 1.22. Synonymous variants: 48 observed, 43.43 expected, observed/expected ratio (o/e) 1.11, 90% interval 0.88 to 1.41.
Homologues: Orthologues: macaque C9H10orf53 (97% identical), dog C10orf53 (89% identical), pig C10orf53 (84% identical), chimpanzee C10H10orf53 (80% identical), rat C16h10orf53 (78% identical), guinea pig C10orf53 (77% identical), mouse 1700024G13Rik (77% identical), tropical clawed frog c7h10orf53 (65% identical), zebrafish C13H10orf53 (61% identical).